SNORA35 (small nucleolar RNA, H/ACA box 35)
Synonyms: HBI-36; SNORA35A
Gene: Small nucleolar RNA gene on chromosome X (114,630,797 to 114,630,924, forward strand). Ensembl gene ENSG00000208839.
Gene Ontology:
Biological process: RNA processing
Cellular component: nucleolus
Homologues: Orthologues: chimpanzee SNORA35 (99% identical), macaque SNORA35 (98% identical), rabbit SNORA35 (88% identical), guinea pig SNORA35 (84% identical), mouse Snora35 (82% identical), rat Snora35 (79% identical). Paralogues in human: SNORA35B (55% identical).
Diseases named in the same sentence as SNORA35 in open-access papers:
SNORA35 is named in the same sentence as 1 disease in open-access papers, as found by Europe PMC text mining. Sharing a sentence is not in itself a finding about the gene and the disease. The quoted sentences say what the papers report.
tumor (1 paper, 2025). "snoRA35 is predicted to pseudo-uridylate the nucleotide 566 in 18S and could drive an essential difference between neuronal and tumor cells." (PMID 41510246, 2025).